BTK (Bruton tyrosine kinase)
Diseases named in the same sentence as BTK in open-access papers (continued):
Sharing a sentence is not in itself a finding about the gene and the disease.
tumor (continued). "In lieu of depleting Breg cells, inhibitors of MEK, BTK, and STAT3 have been reported to hinder Breg formation and promote anti-tumor immunity across various mouse tumor models." (PMID 37868967, 2023). "Fourth, PDLS recapitulate in vivo responses to biological agents targeting tumor cells and TME such as ibrutinib, and represents a platform to study novel combination of BTK inhibitors." (PMID 37031299, 2023). "The novel BTK/PI3K/BRD4 inhibitor, SRX3305, demonstrates marked anti-tumor properties in preclinical models of CLL." (PMID 35743155, 2022). "IBR is a small molecule inhibitor of bruton tyrosine kinase (BTK), which is overexpressed in TAMS and contributes to immunosuppression and tumor growth." (PMID 35701781, 2022). "Through complementary mechanisms, combined use with BTK inhibitors can enhance the sensitivity of DLBCL cells, overcome drug resistance, and enhance tumor lethality." (PMID 35303910, 2022). "To clarify the correlation between 7 PRGs (BTK, CASP5, EEF2K, GZMA, NR1H2, RIPK3, and SDHB) derived from LASSO Cox regression analysis and immune infiltration in COAD, we applied Tumor Immune Estimation Resource (TIMER) database on these genes." (PMID 35912258, 2022). "Cysteine to serine mutations at the C481 site permits downstream signalling, including PLCγ2 and CARD11, activation, hence bypassing the inactive BTK promoting distal BCR signalling activation, resulting in tumour cell proliferation, and migration." (PMID 33122850, 2021). "BTK (Bruton’s tyrosine kinase) is critical for signal transduction downstream of the pre-B cell receptor (pre-BCR) and functions as a tumor suppressor in B-ALL42,43." (PMID 34764253, 2021). "Mechanistically, ibrutinib or acalabrutinib potently inhibits BTK phosphorylation and its downstream oncogenic pathways such as the PI3K-mTOR and MEK/MAPK pathways, resulting in impaired tumorigenicity of these tumor cells." (PMID 34778053, 2021). "In the TGGA, BTK had low expression in tumor tissues of LUAD patients, and patients with high gene expression of BTK had significantly longer survival time." (PMID 34805160, 2021). "Altogether, the study suggested that inhibition of BTK in dendritic cells enhanced maturation and activation of dendritic cells and accelerated CD4+ T cell growth, which contributes to reshaping the tumor microenvironment during cancer development." (PMID 34063667, 2021). "Among these compounds, derivative 16 exhibited potent BTK inhibition (IC50 = 27 nM), high selectivity, antiproliferative effects in primary patient tumor cells, and strong apoptosis induction in Jeko-1 and Z138 cells." (PMID 34885993, 2021). "To further investigate the interaction of the four factors, we analyzed the expression levels of BTK, CCR2 and SCLM4 in KLRG1 knockdown A549 tumor cells." (PMID 34187403, 2021). "SY-1530 inhibits the phosphorylation of BTK and the activity of BTK downstream kinases such as PLCγ2 and ERK, thus blocking the BCR signaling pathway and suppressing tumor growth in B-cell malignancies." (PMID 34264564, 2021). "Specifically, administration of either a PI3Kγ inhibitor or BTK inhibitor (ibrutinib) to PDAC-bearing mice repolarized TAMs towards a Th1 phenotype and led to CD8+ T cell cytotoxicity and reduced tumor burden." (PMID 33924237, 2021). "In summary, the small molecules induced degradation of BTK, CDK4/6, BCR-ABL and BRAF in cancer cells had a better anti-tumor cell proliferation effect than simply inhibiting, and they also demonstrated promising power in overcoming tumor drug resistance." (PMID 34249939, 2021). "The results showed that knockdown of KLRG1 also reduced the expression of BTK and CCR2 in A549 tumor cells." (PMID 34187403, 2021).
tumor (continued). "Further, BTK was found to be co-expressed to differing degrees with SOX2, CD163, or CD68, indicative of both tumour and immune cell expression of the kinase." (PMID 34645618, 2021). "While aberrant BTK activation and expression have been reported in malignant B-cells, it is generally considered that many B-cell tumors are addicted to BTK, since intact BCR-signaling is needed for tumor cells to thrive." (PMID 33526860, 2021). "The expression level of BTK in tumor tissues of male LUAD patients was lower than that in normal tissues (p < 0.05), and male LUAD patients with high level of BTK exhibited a better overall survival (p = 0.035)." (PMID 34863300, 2021). "Binding to BTK inhibits downstream signaling such as MAPK, PI3K, and NF-kB, and reduces migration and proliferation of the tumor cell." (PMID 32025827, 2020). "In lymphocytes, the TEC family tyrosine-kinase proteins BTK (bruton tyrosine kinase), ITK (IL2 inducible T-cell kinase), and TEC are PI3K effectors that are activated by PIP3, with potential anti-tumor therapeutic implications." (PMID 32033478, 2020). "Thus, BTK might play a double-face role in tumor, either promoting survival or inducing apoptosis." (PMID 32351880, 2020). "A combination of an HDAC inhibitor and a BTK inhibitor inhibited UPR and BCR pathways, which reduced tumor growth." (PMID 32575557, 2020). "Therefore, after showing that the combination of selinexor and ibrutinib restrains tumor growth and prolongs mice survival, and since both drugs are able to inhibit BTK, we hypothesized that these drugs could also cooperate to modify the innate immune response in PCNSL." (PMID 32691208, 2020). "Inhibition of BTK with an FDA-approved inhibitor, ibrutinib, restores T cell-dependent anti-tumor immune responses, and potentially inhibits the progression of solid tumors." (PMID 32824865, 2020). "One of such proteins is the Bruton’s tyrosine kinase (BTK), which has recently been shown to have a crucial role in tumour suppression pathways, despite its well-characterized oncogenic activity in blood malignancies." (PMID 30337526, 2018). "Our investigations further highlighted that concomitant disruption of BTK and Bcl-2 with sub-IC50 doses of ibrutinib and venetoclax, respectively, synergistically induce tumor cell lethality in WT and ibrutinib-resistant cells." (PMID 28548645, 2017). "Gene set enrichment analysis (GSEA) and xCell deconvolution were used to evaluate associations with cell proliferation, immune infiltration, and tumor microenvironment (TME) composition while single-cell sequencing datasets (SCP1039, SCP1106) were used to identify BTK-expressing cell populations." (PMID 41822319, 2026). "Additionally, PTGER4‐high tumours exhibited sensitivity to 12 targeted therapies, including MEK inhibitors (Trametinib) and BTK inhibitors (Ibrutinib), suggesting combinatorial therapeutic strategies." (PMID 41284374, 2025). "While BTK inhibitors have shown efficacy in subsets of ABC-DLBCL, their activity as single agents is frequently limited by the emergence of adaptive resistance and incomplete suppression of tumor survival programs." (PMID 41173858, 2025). "In preclinical models, BGB‐16673 effectively degraded both wild‐type BTK and various BTK mutant forms resistant to covalent and noncovalent BTK inhibitors (BTKi), resulting in significant tumour suppression." (PMID 40619749, 2025). "In addition, BTK was shown to function in monocyte/macrophage cell populations, which represent a relevant component of the CLL tumor microenvironment." (PMID 38469232, 2024). "Specifically, BTK shows higher activation in CD20+ B-lymphocytes within PDAC than peripheral leukocytes, playing a crucial role in Breg cell differentiation and the mobilization of myeloid cells to the tumor site." (PMID 39682280, 2024). "All patients had a rapid and sustained reduction in BTK protein due to degradation, regardless of tumor type, drug dose or baseline BTK level." (PMID 39456530, 2024).
tumor (continued). "Collectively, BTK inhibition by tirabrutinib led to the suppression of NF-κB and ERK signaling, followed by downregulation of IRF4- and MYC-targeted genes, resulting in anti-tumor activity in TMD8." (PMID 36897912, 2023). "Therefore, it can be concluded from our experiments that BTK is lowly expressed in NSCLC, and overexpression of BTK suppresses the tumor phenotype of NSCLC cells." (PMID 37638060, 2023). "As this reduction was detected in patients who just completed 2 months BTK inhibitor treatment when most of patients still had lymphocytosis, these phenotypic changes on T cells were independent of tumor load." (PMID 37771591, 2023). "Moreover, an apparent good novelty is the body of data that suggests that the BTK and PI3K inhibitors, which are currently in use to treat the disease, are also effective on the tumor microenvironment, additionally limiting the disease-associated bone lesions." (PMID 37894425, 2023). "From these studies, one can speculate that BTK-IDO may be a universal signaling pathway promoting immunosuppressive responses in various cell types, which may be a potential target of tumor therapy." (PMID 37277776, 2023). "We hypothesize that BTK and DPEP2 genes may alter the immune microenvironment of tumors by affecting the function of macrophages and the anti-tumor therapeutic effect, which deserves further research." (PMID 36991102, 2023). "Our data suggest that BTK influences NF-κB expression as well as pro-inflammatory cytokine secretion by HNSCC tumor cells, which could have influence on tumor cell plasticity and heterogeneity in an autocrine manner." (PMID 37685940, 2023). "The results imply that BTK and DPEP2 may regulate the abundance of immune infiltration and promote anti-tumor immunity by affecting the function of macrophages and monocytes." (PMID 36991102, 2023). "It is mainly due to the fact that BTK is expressed not only in B-cells but also in other types of immune cells such as MDSC, dendritic cells, mast cells, and macrophages, all of which are components of the tumor microenvironment in solid tumors." (PMID 36903645, 2023). "Additionally, BTK knockdown and MALT1 knockout markedly impaired MCL tumor migration and dissemination, and MALT1 pharmacological inhibition decreased MCL cell viability, adhesion, and migration by suppressing NF-κB, PI3K/AKT/mTOR, and integrin signaling." (PMID 36719376, 2023). "BTK inhibitor possesses complex interaction with CAR-T cells, which might optimize its proliferation and high tumor clearance effect under multiple preclinical trials." (PMID 36275715, 2022). "The mechanism of incorporating of BTK inhibitor and PD-1 antibody may promote CAR-T cells’ efficacy by improving the tumor microenvironment." (PMID 36275715, 2022). "Indeed, it is now well known that selective inhibition of BTK (or PI3Kdelta) within the BCR (or CXCR4) pathways leads to peripheral lymphocytosis by disrupting the interaction between the TME and tumor B cell and their homing." (PMID 35804999, 2022). "In particular, BTK is activated in CD20+ B lymphocytes infiltrating PDAC compared to peripheral leukocytes and plays an important role in the differentiation of Breg cells and in the recruitment of myeloid cells to tumor site." (PMID 35359944, 2022). "Altogether, these results revealed that KLRG1, BTK and CCR2 may interact through cell surface receptor signaling pathway to influence the proliferation of tumor cells or affect the immune response indirectly." (PMID 34187403, 2021). "Furthermore, administration of tirabrutinib to the KrasG12D orthotopic mouse model reduced tumor cell growth and infiltrating regulatory B cells with increasing numbers of CD8+IFNγ+ T cells, thus also indicating BTK’s role in immune function." (PMID 34063667, 2021). "Bruton’s tyrosine kinase (BTK) is a non-receptor tyrosine kinase that plays a crucial role in the proliferation and survival of malignant B cells and their interactions with the tumor microenvironment." (PMID 33799793, 2021).
tumor (continued). "BTK inhibitors, such as Ibrutinib and other CXCL13 and CD20 antibodies could reduce tumor progression in B-cell leukemias." (PMID 33324975, 2021). "BTK has also been shown to have a strong effect on myeloid-derived suppressor cells (MDSCs) that inhabit the BMM, inhibiting T cell function and contributing to tumor progression." (PMID 34071917, 2021). "The most active compounds were compounds 31a (IC50 = 5.2 nM) and 31b (IC50 = 4.9 nM) that inhibited BTK auto-phosphorylation, blocked the cell cycle in the G0/G1 phase, induced apoptosis in the TMD8 cells, and suppressed the tumor growth in a TMD8 cell xenograft model." (PMID 34885993, 2021). "Additionally, targeted inhibition of BTK delayed PDAC tumor growth and provided enhanced anti-tumor immunity within the TME of this malignancy." (PMID 34503244, 2021). "Some targeted therapies, such as Bruton’s tyrosine kinase (BTK) inhibitors or immunomodulatory drugs (IMIDs), may have an “on-target, off-tumor” effect on the PCNSL tumor microenvironment." (PMID 34680209, 2021). "In addition to B cells, BTK is also expressed in other types of immune cells including MDSC, dendritic cells, mast cells and macrophages, all of which comprise the tumor microenvironment in solid cancers." (PMID 34063667, 2021). "However, to better reconstitute the heterogeneity of GBM tissue and the tumour microenvironment we would propose to develop cancer cell lines that are BTK+/SOX2+ and BTK−/SOX2+, along with BTK+/CD163+ and BTK−/CD163+ immune cell populations." (PMID 34645618, 2021). "Chemotaxis is also involved in the “Role of tumor-infiltrating B cells in anti-tumor immunity” pathway map and includes BTK and JAK3, but does not include ITK." (PMID 34803999, 2021). "Additional evidence for a potential role of the BCR pathway in the pathogenesis of MCL was provided by phospho-proteomic analysis of MCL cell lines and primary tumor samples demonstrating constitutive activation of multiple BCR signaling molecules, including CD79B, LYN, SYK, BLNK, BTK, and PLCγ2." (PMID 32481736, 2020). "BTK is a non-receptor kinase that plays an essential role in the proliferation of numerous B cell malignancies and is also an important component of the tumor microenvironment." (PMID 33633568, 2020). "Additional support for an involvement of the BCR pathway in the pathogenesis of WM came from observations that a number of BCR signaling molecules, including SFK, SYK, BTK, BLNK, PLCγ2, ERK, AKT, and NF-κΒ, are constitutively activated in primary WM tumor cells." (PMID 32481736, 2020). "A careful monitoring of the cancer load in these animals will be crucial to confirm that BTK inhibitors do not interfere with critical tumour suppressor functions." (PMID 31736210, 2020). "Inhibition of BTK has now also extended into the field of solid tumors, following insights into the role of BTK in various cells of the tumor microenvironment and in non-hematological tumor cells when ectopically expressed." (PMID 29455639, 2018). "The complexity of BTK functions is just beginning to emerge and several papers indicate that, depending on the context, BTK would not be oncogenic but would contribute to tumour suppressor pathways instead." (PMID 30337526, 2018). "Therefore, we assessed here the simultaneous inhibition of BTK and the protease MALT1 that acts downstream of CARMA1 and is essential for ABC DLBCL tumor growth." (PMID 26540570, 2015).
tumor (continued). "B regulatory cells are indeed present in PDA, and the use of an inhibitor of the Bruton tyrosine kinase, which promotes the differentiation of regulatory B cells, has displayed promising results in terms of PanIN lesions reduction and of IFN‐γ‐CD8+ T cells influx into the tumour." (PMID 40831074, 2025). "It includes CD40 agonists, CSF-1R inhibitors, CD11b agonists, CCR2 inhibitors, BTK inhibitors, and emerging chemokine receptor inhibitors, such as CXCR2 and CXCR4 antagonists, highlighting the diverse immune modulating approaches to reprogram the immunosuppressive tumor microenvironment." (PMID 40458409, 2025). "However, inhibitors of BTK and other kinases are typically cytostatic rather than cytotoxic, leading to slow, often lasting significant tumor volume shrinkage." (PMID 38965536, 2024). "Notably, rapid and robust BTK degradation was observed in all patients regardless of the tumor type." (PMID 39456530, 2024). "In contrast to the changes in lactate, alanine, and total choline concentrations, we did not observe significant changes in taurine concentrations in any of these MCL cell populations (data not shown), confirming that BTK inhibition exerts a broad but not universal impact on tumor metabolism." (PMID 38965536, 2024). "Interestingly, mutations in BTK and PLCG2 were not identified; however, resistant cases showed upregulation of the PI3K/AKT/mTOR signaling pathway, leading to increased tumor cell survival." (PMID 38542207, 2024). "However, a comprehensive analysis by both phosphoproteomics and transcriptomics in ABC-DLBCL treated with BTK inhibitors exploring anti-tumor mechanisms has not been reported." (PMID 36897912, 2023). "No co-expression of both oncogenic BTK isoforms in one tumor entity has been described so far." (PMID 36612306, 2023). "Besides BTK inhibition, it also affects other TEC family kinases, such as interleukin-2-inducible T-cell kinase (ITK), and therefore modifies cell adhesion within the tumor microenvironment as well as modulates chemotaxis and cell-to-cell signaling." (PMID 36903645, 2023). "However, comprehensive analysis by both phosphoproteomics and transcriptomics in ABC-DLBCL cell lines to elucidate the anti-tumor mechanism of BTK inhibitors has not been reported previously." (PMID 36897912, 2023). "The results from HPA database showed that the immunohistochemical staining intensity of SDHB, GZMA, BTK, EEF2K, and NR1H2 in glandular cells of normal tissues was stronger than tumor cells, demonstrating that these genes were significantly expressed in normal colon tissues than in tumor tissues." (PMID 35912258, 2022). "Three patients either died before being biopsied or failed to be biopsied due to lesions close to vital organs; 1 patient was biopsied but no viable tumour tissue was obtained since he was previously treated with a BTK inhibitor and glucocorticoid in another hospital." (PMID 34272481, 2022). "Because BTK is expressed in B cells and macrophages, and their crosstalk results in polarization of macrophages to a M2-like tumor-promoting endotype, Ibrutinib treatment of a mouse PDAC model restored T cell-dependent anti-tumor responses and enhanced sensitivity to standard of care gemcitabine." (PMID 36175961, 2022). "Our observation that BTK expression was lower in GBM cell lines compared to GBM tissue samples may reflect that its expression is in a non-cancer cell type or the GBM stem-like cells from a BTK-negative tumour niche." (PMID 34645618, 2021). "However, it should be noted that there are controversial reports regarding the expression of BTK in tumor cells derived from non-hematopoietic lineages." (PMID 34778053, 2021). "Other immune infiltrates, such as macrophages or microglia, within the GBM tissue may instead contribute to the observed BTK activity in GBM tumour tissue rather than GBM-derived cancer cells." (PMID 34645618, 2021). "Thus, BTK appears to serve as a key regulator of TAM crosstalk and anti-tumor immune responses." (PMID 33818636, 2021).